IL10 (interleukin 10)
Diseases named in the same sentence as IL10 in open-access papers (continued):
Sharing a sentence is not in itself a finding about the gene and the disease.
autoimmune disease (continued). "miR-21 has also been shown to act as an upstream regulator of IL-10, specifically as a negative regulator of IL-10-producing regulatory B (IL-10+ Breg) cells which promote tolerance in autoimmune diseases." (PMID 31497013, 2019). "TLR2/4 activation causes a proinflammatory response in autoimmune diseases and contributes to an obesity-induced inflammatory response by increasing TNF-a and IL-6 levels in RA and TNF-a, IL-6, IL-23, and IL-10 levels in SLE." (PMID 31788032, 2019). "The powerful immune downregulation quality of IL-10-producing Bregs has already been shown in various autoimmune diseases, such as EAE, collagen-induced arthritis, lupus and inflammatory bowel disease." (PMID 32038631, 2019). "Our findings indicate that HIF-1α is a key element for IL-10-producing B cell proliferation and IL-10 signaling, thereby influencing the course of T cell mediated autoimmune diseases such as EAE and arthritis." (PMID 31225473, 2018). "Our findings of synergistic regulation of humoral immunity by TGF-β and IL-10 via regulating cellular metabolism provide novel insights for clinical applications of inhibitory cytokines on autoimmune diseases." (PMID 29963056, 2018). "We identified HIF-1α as a critical transcriptional factor involved in IL-10 production by B cells, thereby influencing the course of T cell-mediated autoimmune diseases such as EAE and arthritis." (PMID 29343683, 2018). "In the next sections, the role of IL-10+ Th17 cells in several autoimmune diseases and disease models, such as EAE, type 1 diabetes (T1D), RA, IBD, and psoriasis, will be elaborated." (PMID 29892286, 2018). "In this review, we consider the regulatory function of IL-10-producing Th17 cells in autoimmune diseases and the potential factors and signaling mechanisms that can induce IL-10+ Th17 cells." (PMID 29892286, 2018). "In patients with various underlying medical conditions, ranging from autoimmune disease to cardiac disease, use of statins resulted in decreased IL6, IL10, IP10, MMP2 and MMP610–12." (PMID 30464247, 2018). "Given the centrality of IL-10 in the suppression of the inflammatory response in transplantation rejection and several autoimmune diseases, we investigated IL-10-producing regulatory T cells (Treg) by flow cytometry." (PMID 30526632, 2018). "In this study, we delineate the function of HIFs in B cells during autoimmune disease with a particular interest in IL-10-producing CD1dhiCD5+ B cells." (PMID 29343683, 2018). "Next, we delineated the physiological relevance of the immunoregulation of HIF-1α on IL-10-producing B cells and the protective role of HIF-1α-deficient B cells in autoimmune disease." (PMID 31225473, 2018). "Nevertheless, several studies have shown that IL-10 level is elevated in some autoantibody-mediated autoimmune diseases, such as SLE and pemphigus vulgaris, and reduced IL-10 production is usually associated with remission." (PMID 29335495, 2018). "We identified HIF-1α as a critical transcriptional factor involved in IL-10 production by B cells, thereby influencing the course of autoimmune diseases." (PMID 31225473, 2018). "Some animal models of autoimmune diseases have revealed that the regulatory B cells produce IL-10 and can suppress inflammatory processes." (PMID 30205552, 2018). "The regulatory function of IL-10+ Th17 cells has been extensively characterized in inflammation, cancer, and autoimmune diseases." (PMID 29892286, 2018). "Herein, we describe a novel molecular mechanism of immune modulation, which determines the function of IL-10-producing B cells and thereby influences the course of autoimmune disease." (PMID 29343683, 2018). "In the recent years, different subpopulations of IL-10-secreting B cells have been described in the mouse and their regulatory capacity has been demonstrated in models of infection and autoimmune diseases." (PMID 29403470, 2017).
autoimmune disease (continued). "Since IL-10 is postulated to function as a negative regulator in some autoimmune diseases, the intracellular IL-10 by CD4+ T cells and Tregs was also investigated." (PMID 29312539, 2017). "Previous studies have shown that IL-10 producing regulatory T cells were able to prevent or suppress autoimmune diseases." (PMID 28455817, 2017). "In a previous study, the production of IL-10 was found to be higher in RA, primary Sjogren’s syndrome (SjS) and SLE pointing to B cell hyperactivity as the cause of these autoimmune diseases." (PMID 28265257, 2017). "IL-35 suppresses autoimmune diseases while preventing host defense to infection and promoting tumor growth and metastasis by converting resting B and T cells into IL-10-producing and IL-35-producing regulatory B (Breg) and T (Treg) cells." (PMID 28959012, 2017). "Accordingly, there is a long-standing interest in exploiting the anti-inflammatory properties of IL-10 for immuno-intervention in autoimmune diseases." (PMID 29236056, 2017). "IL-10 is an immunosuppressive cytokine produced and sensed by many immune cells and exerts a protective role in autoimmune diseases." (PMID 28415811, 2017). "Evidence supports that regulatory B cells (Bregs) produce negative regulatory cytokines, such as IL-10, which can negatively regulate immune responses in inflammation and autoimmune diseases." (PMID 28243231, 2017). "Regulatory interleukin-10 (IL-10)-producing B cells (B10 cells) play a critical role in preventing and curing autoimmune diseases in experimental mouse models." (PMID 28824639, 2017). "A high level of IL-10 was produced after damage and IL-8 was significantly increased in local inflammation, serum and body fluid because of infection, and some autoimmune diseases." (PMID 28337225, 2017). "Abnormalities in IL-10-producing regulatory B cells contribute to the development and progression of autoimmune diseases." (PMID 28824639, 2017). "IL-10-producing regulatory B (IL-10+ Breg) cells promote tolerance in autoimmune diseases and transplantation." (PMID 29212210, 2017). "Given the centrality of IL-10 in the suppression of inflammatory responses in several human and experimental autoimmune diseases, we validated the FACS data showing expansion of IL-10-producing regulatory T cells by RT-PCR and ELISA." (PMID 28959012, 2017). "There has been a wide debate about the identification of Bregs and the role of IL-10 in autoimmune diseases." (PMID 28265257, 2017). "Interleukin 10 (IL-10) is a potent anti-inflammatory cytokine that plays an essential, role in preventing inflammatory and autoimmune diseases." (PMID 29190740, 2017). "In this respect, IL-10 impacts autoimmune disease pathology differently depending on which cell and/or mechanism drives a disease." (PMID 28456914, 2017). "The interplay between NFATc1 activity and IL-10 production is not only restricted to the generation of psoriasis-like symptoms but also involved in other autoimmune diseases." (PMID 27222343, 2016). "Several B-cell subsets can produce IL-10 on stimulation in vitro, and protect recipient mice from autoimmune disease on adoptive transfer." (PMID 27396388, 2016). "Over recent years, IL-10-producing B cells have been shown to protect against autoimmune diseases, including EAE." (PMID 26756931, 2016). "Not only functional defects but also a numerical reduction has been described for CD19+CD24hiCD38hi immature B-cells and IL-10 producing Breg cells in autoimmune diseases, including SLE and multiple sclerosis." (PMID 27045291, 2016). "B cells can also induce and maintain tolerance by production of anti-inflammatory cytokines such as IL-10, and B cells genetically or otherwise manipulated to produce IL-10 have immunoregulatory properties in autoimmune diseases." (PMID 27301320, 2016).
autoimmune disease (continued). "Bhan and his colleagues first introduced the “regulatory B cells” (Bregs) based on their feature of secreting IL-10 in chronic colitis in 1997 and pointed out that Bregs play an important role in autoimmune diseases." (PMID 27868072, 2016). "Our results show that IFNα/β induced IL-10 production from macrophages and Th17 cells, which in turn negatively regulated Th17 function in autoimmune diseases such as Experimental Allergic Encephalomyelitis (EAE), an animal model of human MS." (PMID 27308096, 2016). "Interleukin-10 (IL-10), a cytokine with anti-inflammatory properties, plays a crucial role in preventing various inflammatory pathologies especially in tumor and autoimmune diseases." (PMID 26942885, 2016). "IL-22 is a member of IL-10 cytokine family that was discovered to be mainly produced by CD4+ T cells and associated with several autoimmune diseases such as inflammatory bowel diseases (IBD), psoriasis and systemic lupus erythematosus (SLE)." (PMID 27467597, 2016). "Based on data showing that IL10 producing Tregs contributed to the effective control of several autoimmune diseases, a recent study investigated the role of this cytokine in newly diagnosed ITP patients." (PMID 27807534, 2016). "In particular, the production of IL10 and the presence of Bregs in autoimmune disease are currently under investigation." (PMID 27044386, 2016). "There has been extensive debate about the identification of Bregs and the role of IL-10 in autoimmune diseases." (PMID 26137596, 2015). "Little is known about the ability of self-antigens to induce IL-10+ B cells in Graves’ disease (GD), Hashimoto’s thyroiditis (HT), or other autoimmune disease." (PMID 26016954, 2015). "Functional defects in IL-10-producing CD4+ Tr1 cells have also been described in many autoimmune diseases." (PMID 25852682, 2015). "Suppression of Th1 and Th17 responses as well as attenuation of EAE, a murine model of the human autoimmune disease multiple sclerosis, was maintained in IL-10 knock-out mice infected with the liver fluke Fasciola hepatica." (PMID 26377648, 2015). "After that, the regulatory role of IL-10 secreted by B cells was confirmed in several human autoimmune diseases such as lupus, EAE, and IBD." (PMID 26244559, 2015). "Our findings of the IgG-bound platelet-induced conversion of monocytes to regulatory cells open a new avenue for the development of IL-10-inducing therapeutic strategies for inflammation, autoimmune diseases and cancer." (PMID 25896516, 2015). "It has been shown that interleukin 10 (IL-10)-producing regulatory B cells (B10 cells) can negatively regulate cellular immune responses and inflammation in autoimmune diseases." (PMID 26236564, 2015). "The genetic associations between IL-10, TNF/LTA, and CTLA-4 polymorphisms have been investigated extensively in many autoimmune diseases and malignancies, and have been confirmed for certain diseases." (PMID 26108796, 2015). "In most autoimmune disease models studied so far, this suppressive or regulatory role of B cells is mediated by the production of IL-10, which inhibits both Th1 and Th2 polarization, Ag presentation and pro-inflammatory cytokine production by myeloid cells." (PMID 26236564, 2015). "Bregs exert an immunosuppressive effect in autoimmune disease by secreting IL-10 6, 7 or by promoting the generation of immunosuppressive regulatory T cells (Tregs) in cancer." (PMID 26193241, 2015). "The report showed that IL-10 gene knockout mice develop autoimmune disease which indicated that IL-10 played a critical role in autoimmunity." (PMID 24816862, 2014). "Polymorphisms in this gene were described as associated with several autoimmune disease, including SLE, rheumatoid arthritis, psoriasis and Crohn's disease, highlighting that IL10 is one of the common risk genes." (PMID 25369137, 2014). "IL-10 is an anti-inflammatory cytokine and contributes significantly in the suppression of autoimmune diseases." (PMID 25144738, 2014).
autoimmune disease (continued). "We found that IL-10-producing B cells from HIV-1 infected individuals were enriched in TIM-1+ B cells, similar to what was shown in mouse IL-10-producing Bregs in autoimmune diseases." (PMID 24586620, 2014). "IL-10-producing Breg cells have been found to be able to modulate autoimmune disease by affecting the frequency and equilibrium of both Treg cells and Th17 cells." (PMID 24945741, 2014). "Functional studies on IL-10 suggest that it has immunosuppressive properties and can prevent the development of Th1-mediated autoimmune diseases." (PMID 24507659, 2014). "IL10 overexpression can result in exacerbated inflammatory response leading to the development of hyper inflammatory disorders such as autoimmune diseases, a well known phenomena observed in individuals with DS." (PMID 25222269, 2014). "Several studies of human autoimmune disease have revealed that the level of IL-10 detected in patient samples correlates inversely with disease severity." (PMID 23755052, 2013). "Interleukin-10 (IL-10) producing B cells (B10) have been shown to regulate inflammation and autoimmune diseases as well as innate and antigen-specific adaptive immune responses." (PMID 24106222, 2013). "In recent years, subsets of B cells with immunoregulatory properties have been identified in murine models of autoimmune disorders, and these cells downregulate immune responses via secretion of IL10." (PMID 23755918, 2013). "The established association of IL10 with SLE and other autoimmune diseases led us to fine map causal variant(s) and to explore underlying mechanisms." (PMID 24130510, 2013). "It is however of note that IL-10-producing CD8+ T cells have recently been shown to play an essential role in the recovery from EAE, another CNS autoimmune disease that shares essential attributes of the immune-pathogenic mechanisms with EAU." (PMID 24204098, 2013). "IL-10 produced by monocytes and cells other than T cells is required to maintain Treg-suppressive function and other autoimmune diseases." (PMID 24350284, 2013). "This makes antigen-SIT a very attractive approach to realize the potential of IL-10 modulation in the treatment of autoimmune diseases." (PMID 23755052, 2013). "While TNF-α contributes to the inflammatory process, IL-10 has an important role in modulating the inflammatory response and autoimmune disease." (PMID 22454760, 2012). "One possible IL-10-independent mechanism of B cell regulation of autoimmune diseases is via the production of antibodies." (PMID 23189166, 2012). "Transfer of wild-type B cells, but not IL10-negative B cells, reversed the inflammatory response, and IL-10 producing B cells were shown to suppress inflammation in mouse models of autoimmune diseases." (PMID 23807906, 2012). "IL-10-producing regulatory B-cells have been described in healthy individuals, as well as in patients with autoimmune disease." (PMID 23194300, 2012). "In a murine model of autoimmune disease, the regulatory function of B10 cells observed in ex vivo suppressive assays and in in vivo adoptive transfers was partially IL-10 dependent." (PMID 23189166, 2012). "Despite these stimulatory functions of IL-10, the effect of IL-10 in most studies of autoimmune diseases is one of regulation." (PMID 22321827, 2012). "Recently, these IL-10-producing B cells, also known as Bregs, were identified in experimental models of autoimmune disease, cancer, and helminth infection." (PMID 23071588, 2012). "The role of IL-10 has been well documented in experimental arthritis and other autoimmune disorders." (PMID 22315945, 2012). "This was consistent with a study of the suppressive effect of GM-CSF on the progress of autoimmune disease, in which IL-10 levels were significantly increased in GM-CSF-treated mice, and IL-10 was shown to be essential for disease suppression in these animals." (PMID 22493704, 2012).
autoimmune disease (continued). "B cell-derived IL-10 can function in the prevention of inflammatory responses in autoimmune diseases as well as in the down-regulation of active disease exacerbation." (PMID 22558358, 2012). "This crucial role of TREGs in suppressing immune responses to self-antigens and in preventing autoimmune disease is done by two different immunoregulatory immunosuppressive or anti-inflammatory cytokines, IL-10 and TGF-β." (PMID 19622600, 2011). "Foxp3+ regulatory T cells play important roles by inducing anti-inflammatory IL-10-producing T cells in various autoimmune diseases." (PMID 22110705, 2011). "Type 1 regulatory T (Tr1) cells, characterized by the secretion of high levels of the anti-inflammatory cytokine interleukin-10 (IL-10), play an important role in the regulation of autoimmune diseases and transplantation." (PMID 21886804, 2011). "Conversely, in vivo treatment with G-CSF in mouse models of stem cell transplantation 26,29,44,45 and autoimmune diseases 46–48 resulted in induction of peripheral tolerance through IL-10-producing T cells." (PMID 20957751, 2010). "HCV-Ag-specific TH17 cells secrete IL17, a cytokine involved in autoimmune diseases and regulated by IL10 and TGF-b." (PMID 21188205, 2010). "This study paves the way to performing feeding studies in mouse models of autoimmune diseases, that will allow the evaluation the immunomodulatory properties and effectiveness of the viral IL-10 in inducing oral tolerance compared to the murine protein." (PMID 19298643, 2009). "One promising immunomodulatory application of IL-10 is to enhance the induction of oral tolerance to co-administered auto-antigens, leading to the prevention or treatment of autoimmune diseases with lower doses of tolerizing protein." (PMID 19298643, 2009). "The susceptible gene region of systemic lupus erythematosus (SLE), a common autoimmune disease, was mapped on chromosome 1q21-q44S, and IL-10 was identified to be located within this region." (PMID 23675088, 2008). "Furthermore, numerous studies in autoimmune diseases have shown altered IL-10 serum levels, suggesting a potential connection between IL-10 and disease progression." (PMID 40160814, 2025). "Consequently, IL-10 manages autoimmune diseases, such as rheumatoid arthritis, by suppressing the immune response, which prevents tissue damage caused by uncontrolled inflammatory responses." (PMID 40305360, 2025). "Therefore, utilizing DC-SIGN-mediated IL-10 secretion as a therapeutic approach has been explored in autoimmune diseases, allergic conditions, and transplant-related therapies." (PMID 40076949, 2025). "Thus, the TFH-TR1 transdifferentiation pathway results in the generation of two distinct autoimmune disease-suppressing, IL-10-producing TR1 subsets that are distinguished by the expression of Foxp3 and Foxp3 target genes." (PMID 40066448, 2025). "IL-10 is an anti-inflammatory cytokine secreted by various immune cells that regulate excessive inflammatory responses by promoting tissue repair mechanisms and preventing autoimmune diseases." (PMID 40722593, 2025). "IL-10 gene transfer studies have demonstrated protective effects against autoimmune diabetes in mice, and recombinant IL-10 has proven safe in clinical trials to treat some autoimmune diseases, with evidence that it enhances pancreatic beta cell response to glucose in vitro." (PMID 41472730, 2025). "Because MSCs can exert immunosuppression through cell–cell contact, downregulation of antigen-presenting and costimulatory molecules, and secretion of anti-inflammatory cytokines like IL-10, they have the potential to treat various autoimmune diseases, such as RA." (PMID 40761339, 2025). "IL‐10 plays a controversial role in inflammatory and autoimmune disorders." (PMID 41006957, 2025). "For example, strategies aimed at enhancing IL-10 production from these cells could be beneficial in treating inflammatory and autoimmune disorders by promoting a more tolerogenic immune environment." (PMID 40076949, 2025).